IFNG (interferon gamma)
Diseases named in the same sentence as IFNG in open-access papers (continued):
Sharing a sentence is not in itself a finding about the gene and the disease.
cancer (continued). "In this context, it would be of interest to evaluate the cytotoxic activity of Mob-MDM(LPS/IFNγ) in vitro against CD24-expressing human cancer cell lines as well as in vivo in humanized mouse cancer models." (PMID 34281268, 2021). "Our studies in CCA cell lines were consistent with previous research in other cancers; we showed that PD-L1 expression was upregulated following IFNγ treatment in two CCA cell lines." (PMID 34083572, 2021). "Treating breast (and other) cancer patients with interferon gamma can help sensitize cancer cells to apoptosis, facilitating their elimination with additional drugs." (PMID 34568068, 2021). "Mutations in the IFNγ receptor IFNGR1, signaling adaptors JAK1 and JAK2 or components of the IFNγ signaling cascade, such as STAT1 and IRF1 were associated with cancer progression and immunotherapy resistance." (PMID 34201655, 2021). "Similar to natural killer cells, γδT cells can kill cancer cells indirectly by releasing abundant amounts of interferon-gamma (IFN-γ) thereby displaying a Th1 cell-like phenotype." (PMID 33653419, 2021). "More specific to cancer, IFNγ induces cell cycle arrest and apoptosis of cancer cells and inhibits angiogenesis." (PMID 33578830, 2021). "It was previously reported that IFNγ decreases the expression of NK group 2 member D (NKG2D) ligands in cancer cells." (PMID 33491334, 2021). "By using the ELISA cytokine (Abcam) kit, results of CAR-T cells' ability to release cytokines IL-2 and IFNg showed that CAR-T cells were capable of releasing these cytokines when interacting with cancer cells A549." (PMID 34189144, 2021). "Other studies have revealed that curcumin can suppress the interferon gamma (IFN-γ)-induced upregulation of PD-L1 expression in cancer cells." (PMID 34248973, 2021). "This highlights that although 1,180 peptides derived from cancer antigens are represented in the HLA-I immunopeptidome under both conditions, IFNγ treatment leads to the presentation of an additional 1,268 peptides derived from cancer antigens." (PMID 33968037, 2021). "PD1 and LAG3 have been reported as the most prevalent T-cell immune checkpoint receptors in RCC, and their blockade to increase IFNγ signaling was considered crucial for successful anti-cancer immunosurveillance." (PMID 34215851, 2021). "Several cancer cell lines showed little surface membrane Fas expression even after treatment with interferon-gamma (IFN-γ)." (PMID 34717628, 2021). "This leads to an increment of PD-L1 expression, with a subsequent uprise in PD-1 antibody blockade, as demonstrated by the administration of the IFNγ-inducing cancer vaccine and nivolumab in combined therapy." (PMID 34335980, 2021). "Interferon-gamma-mediated signaling pathway has been identified as one of the vital signaling pathways in cancer." (PMID 34094918, 2021). "Analysis of the fluorimetry data at day 10 showed that the strongest inhibitory effect on the cancer cell spheroid growth was observed in the sph+SFV/IFNg+Pam3+M0 and sph+SFV/IFNg+Pam3 groups." (PMID 34835178, 2021). "In hepatocellular carcinoma, the exposure of MSCs to IFNγ and TNFα leads to overexpression of TGFβ, which in turn promotes EMT-associated functional alterations in cancer cells." (PMID 33472580, 2021). "Together, these results suggested that our IFNGrGS performed better than the pan-cancer-based IFNG gene signatures in predicting the efficacy of radiotherapy and that a low IFNGrGS score implied an improved overall survival for GBM patients after radiotherapy." (PMID 34566988, 2021). "What is more, TLR ligands (e.g., LPS) either alone or together with IFNγ drive M1 polarization, which further leads to the inhibition of cancer cell growth." (PMID 33919517, 2021). "GL enhances NO production from macrophages stimulated with interferon-gamma (IFN-γ) or lipopolysaccharide (LPS), and the resulting high concentration of NO products kills cancer cells." (PMID 34830916, 2021).
cancer (continued). "We also proposed that OAS1 expression enhancement can induce the anti-cancer effects of interferon-gamma, while suppression of CTSH hinders formation of focal adhesions." (PMID 34249670, 2021). "PD-L1 expression in cancer cells is positively regulated by T cell-derived IFNγ through the JAK-STAT signaling pathway." (PMID 33446805, 2021). "Prostasin is identified as a potent regulator of PD-L1 expression induced by the inflammatory cytokine IFNγ in human lung epithelial and cancer cells." (PMID 34240739, 2021). "IFNγ stimulates MHC-I expression in cancer through multiple ways, of which the induction of NLRC5 expression followed by the formation of CITA enhanceosome is the principal mechanism of IFNγ-induced increase in MHC-I." (PMID 34201655, 2021). "CD8 + T cells have been shown to induce lipid peroxidation in cancer cells and sensitize cells to ferroptosis via IFNγ." (PMID 34284753, 2021). "Trastuzumab-conjugated oNK, ACE-oNK-HER2, executed in vitro and in vivo cytotoxicity against HER2-expressing cancer cells and secretion of IFNγ." (PMID 34072864, 2021). "Our findings lay a foundation for the potential integration of HK M. obuense in specific cell-based immunotherapeutic modalities such as adoptive transfer of Mφs (Mob-MDM(LPS/IFNγ)) for cancer treatment." (PMID 34281268, 2021). "Accordingly, significant decrease in total surface MHC-I was observed in both Ankrd52-null MC38 cancer cells isolated from tumors or cultured with IFNγ stimulation." (PMID 34853298, 2021). "That means blocking IFNγ‐induced overexpression of PD‐L1 in cancer cells theoretically prolongs the effect of immunotherapy." (PMID 33491334, 2021). "SLC7A11 expression in tumors was found to negatively correlate with CD8+ T cell counts and IFNγ expression in tumors, and prognosis of cancer patients." (PMID 33891303, 2021). "Treatment with Gal-3 antagonists promotes T cell infiltration by recognizing cancer-mediated interferon-gamma in vivo." (PMID 34572346, 2021). "Mechanically, radiotherapy can activate Ataxia-Telangiectasia mutated gene (ATM) to produce IFNγ and synergizes with immunotherapy-activated CD8+ T cells to suppress SLC7A11 expression in cancer cells." (PMID 34796174, 2021). "Since T helper 1 phenotype is correlated with inflammatory cytokine production such as IL-12 and IFNγ (which are helpful in cancer therapy), it would be favorable to intensify this phenotype." (PMID 34177890, 2021). "Despite the recent remarkable clinical success of PD-1/PD-L1 ICB, most cancer patients fail to respond or develop treatment resistance, frequently due to defective antigen presentation and IFNγ signaling." (PMID 34853298, 2021). "Once cancer cells are attacked by NK cells and T cells, the cancer cells arm IFNγ‐induced PD‐L1 as a “shield” and escape from host immunity." (PMID 33491334, 2021). "IFNγ has been shown to restore MHC-I expression in cancer cells, suggesting its potential use to correct MHC-I defects." (PMID 33671123, 2021). "We achieved substantial depth at the transcript, protein, and HLA-peptide level and show that IFNγ not only increases antigen presentation but also unveils a suite of novel peptides to the immune system, many of which derive from known cancer antigens." (PMID 33968037, 2021). "CXCL10 and other chemoattractant cytokines are transcriptional targets of the IFNγ pathway and their expression in cancer often correlates with clinical response to immune checkpoint blockade." (PMID 33446805, 2021). "This test was obtained by measurement of the interferon-gamma (IFN-γ) secretion of CD8+ T cells using the A549 cell line (carcinoma cell line) as target cells." (PMID 34298855, 2021). "In the syngeneic mouse model, we evidenced the ability of cancer-specific bcl-2 to impair T cell response, through reduced production of IFNγ and the effector memory T cells population." (PMID 32269145, 2020).
cancer (continued). "Significantly, LmSIY-induced splenocytes were not capable of suppressing Panc02SIY100 growth in vitro unless cancer cells were pretreated with interferon gamma (IFNγ) prior to coculture (Fig. 2Dii)." (PMID 32355214, 2020). "This increase in PD-L1 expression was driven by T-cell-derived IFNγ and observed on both cancer and non-cancer cells, with macrophage PD-L1 expression often protracted compared to cancer cells." (PMID 32992658, 2020). "When CD8+ T cells are activated, such as through the recognition of neoantigens or viral antigens presented by cancer cells, they produce inflammatory cytokines like tumor necrosis factor alpha (TNFα) and interferon gamma (IFNγ)." (PMID 34212113, 2020). "This suggests that IRE1α is an important, IFNγ-independent regulator of CD274 in macrophages in cancer." (PMID 32520957, 2020). "When tested in TICS, cancer cells isolated from patients 1, 2 and 3 induced detectable levels of soluble IFNγ, which were further enhanced after nivolumab treatment." (PMID 32200422, 2020). "Compared to MDSCs from healthy donors, MDSCs from cancer patients suppressed both T cell proliferation and IFNγ production (p < 0.01)." (PMID 32415175, 2020). "This demonstrates that the IFNγ-dependent Trp-catabolizing activity of the primary patient-derived cancer cells can be attributed to IDO1 activity, and can be selectively inhibited by NTRC 3883-0." (PMID 33584686, 2020). "The induction of NGFR by interferon gamma (IFN-γ) in cancer cells 76 suggests a generic stress-induced phenotype." (PMID 32483452, 2020). "Upon T‐cell receptor activation, they produce effector cytokines like IFNγ and kill cancer cells in an antigen‐specific manner via the granzyme/perforin system." (PMID 32821382, 2020). "For example, natural killer (NK) cells can recognize infected and abnormal cells, such as cancer cells and kill these cells by inducing them to undergo apoptosis or by producing cytokines, such as interferon-gamma (IFN-γ)." (PMID 33171663, 2020). "Specifically, interferon alpha and beta (IFNα/β), interferon gamma (IFNγ), and signaling by interleukins were significantly up-regulated in cancer cells isolated from immune-competent mice (SBM)." (PMID 32183351, 2020). "IFNG is a major effector of immune therapy of cancer, and its high expression is correlated with poor prognosis in ccRCC." (PMID 33371886, 2020). "A six color flow cytometry panel and the indicated gating strategy was used to assess the percentage of CD56BrightCD3− and CD56DimCD3− NK cells producing IFNγ in 11 healthy donors and nine cancer patients." (PMID 32508837, 2020). "Combination therapy compared with anti-PD-1 monotherapy showed higher expression levels of PD-L1 on cancer cells due to increased secretion of IFNγ, which increased recruitment of STAT1." (PMID 33584714, 2020). "The healthy donor and cancer patient populations produced intracellular IFNγ in response to both stimuli." (PMID 32508837, 2020). "Other proinflammatory cytokines, such as TNFα and IFNγ, seem to have an ambiguous effect on cancer progression." (PMID 32733461, 2020). "Among the most relevant factors, interleukin (IL)-6, IL-1α, tumor necrosis factor-alpha (TNFα), and interferon-gamma (INFγ) have long been recognized as mediators of cancer cachexia, though several other potential mediators have been identified." (PMID 33330108, 2020). "The magnitude of αPD-1-driven enhancement in lymphocyte activation and IFNγ levels was dictated by the cancer cell-to-lymphocyte ratio." (PMID 32200422, 2020). "Interferon gamma induces DNA damage and promotes senescence of cancer cells through TGF-β/SMAD signaling." (PMID 33336042, 2020). "IFNγ pathway genes also showed greatest expression in cancer cells cultured under syngeneic conditions, with modest up-regulation in immunodeficient in vivo conditions and minimal up-regulation in 3D conditions, relative to 2D." (PMID 32183351, 2020).
cancer (continued). "Collectively, these data demonstrated that SB-3CT treatment reduced IFNγ-inducible PD-L1 expression in a variety of cancer cell lines." (PMID 32988398, 2020). "T cells secrete interferon gamma and stimulate expression of PD‐L1 of neighboring cancer cells, which hinders the PD‐1 ligand on T cells, resulting in T‐cell anergy and apoptosis." (PMID 32941674, 2020). "Neoadjuvant chemoradiotherapy is able to trigger interferon-gamma release from cancer cells and in turn to induce PD-L1 expression." (PMID 32867256, 2020). "Our findings are also in line with a study showing immune-evasion by cancer cells through conversion of NK cells into ILC1-like cells where Eomeslo ILC1s produced significantly lower IFNγ and had reduced cytotoxicity compared to Eomeshi NK cells." (PMID 32625207, 2020). "The extent to which different cancer cells are responsive to IFNγ and the downstream effects of IFNγ exposure vary among cancer types and molecular subgroups within a cancer type." (PMID 34212113, 2020). "The expression of immunoproteasome is significantly upregulated in some cancer cells that endogenously or exogenously induce interferon-gamma (IFN-γ)." (PMID 32235770, 2020). "A lot of genes induced by IFNγ are, in fact, involved in cancer cell immune evasion, such as PDL1, PDL2, CTLA4, and IDO." (PMID 32937860, 2020). "When compared with the untreated mice, the anti-cancer-related cytokines, IL-2 and IFNγ, occurred at a higher level in the serum of CH-treated mice, whereas the amounts were not significantly (p < 0.05) higher in the CL-treated mice." (PMID 30814922, 2019). "The most important soluble factors in cancer-immune system interactions are interferons, and particularly IFNγ produced by T cells and NK cells." (PMID 31355143, 2019). "The direct effects of IFNγ on the NK cytotoxic actions against different cancer cells especially when used in clinical trials are explained." (PMID 31457012, 2019). "Cytokines such as TNF-α, IL-1, IL-6, and interferon-gamma (IFN-γ) are released by both cancer cells and host immune cells (macrophages/lymphocytes)." (PMID 31683709, 2019). "First, if cancer cells have the capacity to respond to IFNγ, they will often up-regulate immune checkpoints on their surface, such as PD-L1, and will effectively shut down effector T cell responses." (PMID 31133614, 2019). "The prominent role for IFNγ signaling in the immune response to cancer cells, both clinically and in our screens, prompted us to define more specifically which NK-92-sensitizing genes are involved in modulating the IFNγ response." (PMID 31452512, 2019). "In summary, our data identify a critical role for IFNγ sensitivity within cancer cells as a major determinant that directly shapes the TME." (PMID 31133614, 2019). "To simplify the model at this stage, we neglected the role of IFNγ released by Teff in regulation of PD-L1 on cancer cells." (PMID 31236847, 2019). "Impressively, the SCNE dramatically depressed key circulating pro-cancer inflammatory cytokines (IFNγ, TNFα, IL-6, IL-1α, and IL-1β) in all of the xenograft and 4NQO-1 mouse models tested." (PMID 31572681, 2019). "These cells secreted less interferon gamma (IFN-γ) after coculturing with cancer cells and showed a decreased expression of perforin and granzyme B. Gulo−/− mice showed a shorter survival time than control animals." (PMID 31934267, 2019). "The anti-CD137 antibodies show great potential in anti-cancer activities due to its ability to activate cytotoxic T cells and to increase the production of interferon gamma (IFN-γ)." (PMID 31013788, 2019). "These analyses suggest that in all three available datasets, TIGS outperforms TMB and other biomarkers that are based on gene-expression profiling (TIDE, IFNG etc.)in accurately predicting clinical response to immunotherapy and in pan-cancer applicability." (PMID 31767055, 2019).
cancer (continued). "We showed that survival of a subset of cancer cells in a low‐adherent state depends on the concerted activity of IFNγ and Erk signalling pathways activated by radiation‐ or chemically induced stress." (PMID 30919591, 2019). "IL-1 signaling has been proposed as a key mediator of host defense against malignancies through its role on NK cell activity (i.e. IFNγ production and ADCC)." (PMID 30890189, 2019). "Pathways relating to cellular immunity also observed in SKOV3, OVCAR3, and OVCAR8 STAT3 KO cells were enriched in four cancer types: interferon gamma response, immune response, immune cell activation and differentiation." (PMID 31534498, 2019). "Our data define responsiveness of cancer cells to IFNγ as a critical determinant for sensitivity to anti–PD-1 therapy." (PMID 31133614, 2019). "This likely reflects the T-cell inflamed nature of HPV+ cancers, and specifically the higher levels of IFNγ expressed in these tumors." (PMID 31394808, 2019). "The importance of the cancer cell IFNγ response prompted us to systemically identify perturbations that modulated IFNγ signaling, as read out by cytokine-induced MHC-I upregulation." (PMID 31452512, 2019). "The abnormal growth of cancer cells can activate neighboring cells, which secrete tissue damage signals, such as interferon gamma (IFN-γ), that activate and recruit NK cells, the primary drivers of immunosurveillance." (PMID 31366131, 2019). "IFNγ binds to cell surface receptors (IFNGR1/IFNGR2) on cancer cells resulting in activation of JAK1 and JAK2 and phosphorylation of STAT1." (PMID 31133614, 2019). "Natural killer (NK) cells make up 25–40% of hepatic lymphocytes, with important roles in protecting against fibrosis and defending against cancer and viruses through potent cytotoxicity as well as production of IFNγ." (PMID 31627733, 2019). "IFNγ has been shown to induce cancer cell dormancy through multiple pathways and, interestingly, to exert different effects in indolent (Ki67low) cells, and in dormant (Ki67−) cells." (PMID 31355143, 2019). "DAMPs not only prime cancer-killing CD8+ T cells for the secretion of interferon γ (IFNγ), but also anti-cancer CD4+ T cells for the secretion of IFNγ and IL-17A." (PMID 31739582, 2019). "An interesting link between IFNγ and CSCs metabolism came from the observation that IFNγ triggers cancer dormancy through indolamine 2,3 dioxygenase (IDO1), an enzyme that catalyzes tryptophan metabolism." (PMID 31355143, 2019). "The induction of an IFNγ signature in CMT167 in vivo suggests that these cancer cells respond to and induce IFN-dependent effectors." (PMID 31133614, 2019). "Treatment of cancer cells with IFNγ led to an increase in PD-L1 in both the cellular and 100k g fractions." (PMID 30951669, 2019). "In this study, we have focused on how cancer cell–intrinsic response to IFNγ affects the TME and response to anti–PD-1 therapy." (PMID 31133614, 2019). "Unfortunately, chronic stimulation of cancer cells with IFNγ can lead to adaptive or acquired resistance." (PMID 31133614, 2019). "CD24-CAR-NK-92 cells specifically produced high amounts of IFNγ upon target presentation by cancer cells." (PMID 30717444, 2019). "This variability likely reflects the complexity of cancer cell IFNγ signaling, which can include MHC upregulation, growth suppression and immunomodulation." (PMID 31452512, 2019). "Consistent with the importance of cancer cell IFNγ signaling, sgRNAs targeting negative regulators of the interferon response were strongly depleted after NK-92 challenge." (PMID 31452512, 2019). "RNA sequencing analysis of cancer cells recovered from lung tumors revealed that CMT167 cells induced an IFNγ signature that was blunted in LLC cells." (PMID 31133614, 2019). "This coordinated upregulation of the mRNA levels of genes involved in the MHC-II antigen presentation pathway and their regulation were correlated with the higher intratumoral levels of IFNγ observed in HPV+ carcinomas." (PMID 31394808, 2019).